DEPDC1 (DEP domain containing 1)
Diseases named in the same sentence as DEPDC1 in open-access papers (continued):
Sharing a sentence is not in itself a finding about the gene and the disease.
lung adenocarcinoma (5 papers, 2020 to 2023). A carcinoma that arises from the lung and is characterized by the presence of malignant glandular epithelial cells. "The expression of DEPDC1 in lung adenocarcinoma tissues is significantly higher than that in adjacent normal tissues." (PMID 34134185, 2021). "The high expression of DEPDC1 is correlated with the tumor size and clinical stage of lung adenocarcinoma and knocking down DEPDC1 inhibits the proliferation of A549 and H1975 cells." (PMID 34134185, 2021). "This study aims to explore the relationship between the expression of DEPDC1 and the clinical prognosis of lung adenocarcinoma, and to preliminarily explore the possibility of DEPDC1 as a potential biomarker and therapeutic target of lung adenocarcinoma." (PMID 34134185, 2021). "DEP domain-containing 1 (DEPDC1) has been proved to be closely related to the occurrence and development of most tumors, and the overexpression of DEPDC1 in lung adenocarcinoma has been preliminarily confirmed." (PMID 34134185, 2021). "DEPDC1 plays an important role in the progression and evolution of lung adenocarcinoma." (PMID 34134185, 2021).
non-small cell lung carcinoma (4 papers, 2020 to 2025). A group of at least three distinct histological types of lung cancer, including non-small cell squamous cell carcinoma, adenocarcinoma, and large cell carcinoma. "Previous studies have demonstrated that DEPDC1 is involved in the malignant progression of multiple tumors, including non-small cell lung cancer (NSCLC), hepatocellular carcinoma." (PMID 40018408, 2025). "Current evidence suggests that DEP domain containing 1 (DEPDC1) has an important effect on non-small-cell lung cancer (NSCLC)." (PMID 38564630, 2024).
osteosarcoma (4 papers, 2023 to 2025). A usually aggressive malignant bone-forming mesenchymal neoplasm, predominantly affecting adolescents and young adults. "A current study has indicated that DEPDC1, one of the hub genes, is highly expressed in osteosarcoma, and its high expression is associated with poor prognosis." (PMID 36849972, 2023). "Importantly, the higher expression levels of DEPDC1 were greatly associated with the decreased survival time of osteosarcoma patients (p < 0.001)." (PMID 36479633, 2023). "Related studies on DEPDC1 in soft tissue sarcoma or osteosarcoma had been published, all of which indicated that DEPDC1 played a significant role in facilitating tumor development." (PMID 40600015, 2025). "In osteosarcoma, the DEPDC1/KIF4A axis promotes malignant behaviours and EMT by inhibiting the Hippo pathway, resulting in decreased p-LATS1/p-YAP levels." (PMID 41361459, 2025). "It is shown that the relative expression level of DEPDC1 in the osteosarcoma group was 2.3 times higher than that in the control group." (PMID 36479633, 2023). "After silencing the expression of DEPDC1, it was also noticed that Ki‐67, a proliferation marker, was significantly down‐regulated in the osteosarcoma tissue." (PMID 36479633, 2023). "Gene expression profile analysis and immunohistochemical (IHC) examination suggested that DEPDC1 is highly expressed in human osteosarcoma cells and tumor tissue." (PMID 36479633, 2023). "The experimental osteosarcoma tumor sizes from the DEPDC1‐knockdown human osteosarcoma cells were dramatically smaller than those inoculated with wild‐type osteosarcoma cells." (PMID 36479633, 2023). "This current study tends to decipher the potentially critical role of DEP domain‐containing 1 (DEPDC1), a tumor‐related gene, during the progression of osteosarcoma." (PMID 36479633, 2023). "Combined with the outcomes of this animal model study, we are the first to report here that the proliferation and migration of osteosarcoma cells are affected by DEPDC1 in in vitro and in vivo settings." (PMID 36479633, 2023). "The silencing of DEPDC1 arrested osteosarcoma cell proliferation, promoted apoptosis, and ceased tumor metastasis." (PMID 36479633, 2023). "Studies involving clinical human osteosarcoma cases exhibited a strong correlation of DEPDC1 over‐expressed osteosarcoma specimens with a reduced patient survival rate." (PMID 36479633, 2023). "Collectively, this study demonstrated that DEPDC1 is a critical driver in the promotion of osteosarcoma progression and results in poor patient prognosis." (PMID 36479633, 2023). "In this study, we found that DEPDC1 is highly expressed in human osteosarcoma through the GEO database analysis and subsequently confirmed its high expression on patient osteosarcoma specimens and commercial osteosarcoma cell lines." (PMID 36479633, 2023). "IHC examination on the clinical osteosarcoma biopsy specimens revealed ubiquitous DEPDC1+ staining compared to the adjacent normal tissue." (PMID 36479633, 2023). "Furthermore, elevated levels of DEPDC1 expression correlated strongly with reduced survival times and poor prognoses in osteosarcoma patients." (PMID 40600015, 2025). "Furthermore, the manipulation of DEPDC1 expression levels by using silencing RNA (siRNA) or lentiviral vector intervention on human osteosarcoma cells was performed to reveal its role and interactions in in vitro and in vivo settings." (PMID 36479633, 2023). "At the same time, DEPDC1 appears to accurately predict the clinical characteristics and prognosis of patients, and may also be critical for osteosarcoma diagnosis and prognosis." (PMID 36479633, 2023). "We hypothesize that DEPDC1 is crucial in the progression and prognosis of osteosarcoma, while the silencing of DEPDC1 expression can halt osteosarcoma cell proliferation and tumor progression." (PMID 36479633, 2023). "Genetically targeting or pharmacologically inhibiting DEPDC1 may serve as a promising strategy for treating human osteosarcoma." (PMID 36479633, 2023).
osteosarcoma (continued). "In this study, we determined that DEPDC1 promotes the proliferation and migration of osteosarcoma cells in vitro and in vivo, which may provide new therapeutic targets for the further development of novel anticancer drugs." (PMID 36479633, 2023). "Also, we found that DEPDC1 promotes the proliferation and migration of osteosarcoma in vitro and in vivo." (PMID 36479633, 2023). "The high expression of DEPDC1 correlated with the reduced survival time of osteosarcoma patients indicates that DEPDC1 is a potential prognostic marker and therapeutic molecular target of osteosarcoma." (PMID 36479633, 2023). "Preliminary data analysis of the online database in our laboratory has suggested that DEPDC1 may also be overexpressed in human osteosarcoma tissue." (PMID 36479633, 2023). "In this study, we determined that DEPDC1 could promote the proliferation and migration of osteosarcoma cells in vivo and in vitro." (PMID 36479633, 2023). "The current investigation is underway to explore how DEPDC1 affects the progression of osteosarcoma and which signaling pathway DEPDC1 participates in the promotion, proliferation, migration, and apoptosis inhibition of osteosarcoma." (PMID 36479633, 2023). "To explore the relationship between the DEPDC1 and the clinicopathological characteristics of osteosarcoma patients, we analyzed the positive staining patterns of DEPDC1 in clinical osteosarcoma specimens that were correlated with patients' disease progression." (PMID 36479633, 2023). "Therefore, we speculate that in human osteosarcoma cells, high expression of DEPDC1 promotes progression and bad prognosis of human osteosarcoma." (PMID 36479633, 2023). "Indeed, ROC curves indicated that the area under the curve (AUC) of the DEPDC1‐based predictions was 0.7908, suggesting that DEPDC1 could be used to predict the survival rate of osteosarcoma patients." (PMID 36479633, 2023). "Besides, DEPDC1 can accurately predict the clinical features and prognosis of patients, which may provide a new target for the diagnosis and treatment of human osteosarcoma." (PMID 36479633, 2023). "The expression of DEPDC1 was upregulated in osteosarcoma cells (U2OS, SaOS-2 and MG-63) compared with that in hFOB1.19 group, and the highest DEPDC1 expression was observed in U2OS cells." (PMID 36849972, 2023). "The expression of DEPDC1 and KIF4A in osteosarcoma tissues and the correlation of them will be investigated in future study." (PMID 36849972, 2023). "Real‐time PCR and western blot assessments on osteosarcoma cell lines (HOS, MG‐63, and Saos‐2) also indicated significant overexpression of DEPDC1 at mRNA and protein levels, in comparison with the human osteoblastic cell line Hfob1.19." (PMID 36479633, 2023). "Furthermore, downregulation of DEPDC1 activated the Hippo signaling pathway, leading to the overexpression of p-LATS1 and p-YAP, which in turn inhibited YAP and suppressed the proliferation of osteosarcoma cells." (PMID 40600015, 2025). "However, there is no published evidence as to whether DEPDC1 plays a role in the development and progression of human osteosarcoma." (PMID 36479633, 2023).
Nephroblastoma (3 papers, 2023 to 2025). An embryonal neoplasm characterized by the presence of epithelial, mesenchymal, and blastema components. "DEPDC1 facilitates the malignant transformation of nephroblastoma by employing the Wnt/β-catenin signaling pathway, which may be modulated by forkhead box transcription factor 3a (FOXO3a)." (PMID 38929279, 2024). "Therefore, DEPDC1 might be explored for its contribution in Wnt/β-catenin modulation and trialed for treatment of nephroblastoma in future." (PMID 38929279, 2024).
ovarian carcinoma (3 papers, 2021 to 2023). A malignant neoplasm originating from the surface ovarian epithelium. "Interestingly, we found that, in the ovarian cancer RNA expression datasheet from the GEPIA database, ZNF839, DEPDC1, and MRC2 were associated with LINC00909 in the RNA level." (PMID 34336102, 2021). "Eight genes (NUF2, GTSE1, DEPDC1, KIF18B, PBK, CEP55, HJURP, SKA1) were potential hub genes correlated to ovarian cancer progression." (PMID 35173547, 2022).
renal cell carcinoma (3 papers, 2024 to 2025). "Clinical tissue samples from patients with renal cell carcinoma revealed that DEPDC1 was associated with unfavorable prognosis and served as a predictor of renal cell carcinoma metastasis." (PMID 40600015, 2025). "Recent studies have shown that DEPDC1 regulates glycolysis in renal cell carcinoma through the AKT/mTOR/HIF1α pathway." (PMID 40722708, 2025). "The next step is to explore how DEPDC1 regulates the AKT/mTOR/HIF1α pathway and key glycolytic enzymes, and to verify the effects of DEPDC1 in primary drug-resistant tumor animal models of renal cell carcinoma." (PMID 39068164, 2024).
ductal carcinoma in situ (2 papers, 2019 to 2020). "Our findings were validated by another study to some extent, and they found DEPDC1, EXO1, RRM2 and some proteins had enhanced expression in the ductal carcinoma in situ and invasive ductal carcinoma." (PMID 31998560, 2020).
endometrial cancer (2 papers, 2020 to 2025). Primary or metastatic malignant neoplasm involving the endometrium (mucous membrane that lines the endometrial cavity). "Another research concerning endometrial cancer found that DEPDC1 is involved in cell proliferation and restrain apoptosis of endometrial cancer cell lines, and it promotes tumor growth through the PCDH10‐DEPDC1‐Caspase signal regulation pathway." (PMID 33140894, 2020).
liver cancer (2 papers, 2022 to 2023). An epithelial or non-epithelial malignant neoplasm that arises from the liver. "Among these characteristic genes, DEPDC1, DEPDC1B, PRR11, and TRIP13 were risk factors for liver cancer patients." (PMID 36785674, 2023). "In liver cancer, the genes DEPDC1, DEPDC1B, PRR11, and TRIP13 have been explored in previous studies." (PMID 36785674, 2023). "Meanwhile, DEPDC1, DEPDC1B, CALCRL, PRR11, and TRIP13 were significantly upregulated in liver cancer tissue, yet NGFR was downregulated." (PMID 36785674, 2023).
lymph node metastasis (2 papers, 2022 to 2023). "Meanwhile, high expression of DEPDC1 was related to lymph node metastasis and advanced stage." (PMID 36768316, 2023). "Furthermore, DEPDC1 was proven to be related to advanced stage cancer and lymph node metastasis." (PMID 36768316, 2023).
melanoma (2 papers, 2014 to 2019). A malignant, usually aggressive tumor composed of atypical, neoplastic melanocytes. "DEPDC1, previously observed to be 12.4-fold downregulated upon loss of p300 in a process that induces cellular senescence in melanoma cells, here was approximately 60-fold downregulated." (PMID 30626320, 2019).
urothelial carcinoma of the bladder (2 papers, 2023 to 2024). "The cancer peptide vaccine S‐288310 containing oncoantigens against DEPDC1 is well tolerated and can effectively prolong the survival time of patients with urothelial carcinoma of the bladder." (PMID 36479633, 2023). "Another cancer vaccine comprising two HLA-A*24:02-restricted peptides from DEP domain containing 1 (DEPDC1) and M-phase phosphoprotein 1 (MPHOSPH1) afforded prolonged survival in CTL-induced patients with advanced urothelial carcinoma of the bladder." (PMID 38990441, 2024).
cholangiocarcinoma (1 paper, 2020). A carcinoma that arises from the intrahepatic biliary tree (intrahepatic cholangiocarcinoma) or from the junction, or adjacent to the junction, of the right and left hepatic ducts (hilar cholangiocarcinoma). "Our analysis suggests that expression of DEPDC1, FUT4, MDK, PACS1, PIWIL4, miR-22, miR-551b, and DNA methylation of cg27362525 and cg26597242 could be explored further as potential biomarkers of cholangiocarcinoma." (PMID 33193605, 2020).
colon cancer (1 paper, 2020). "Another study further confirmed that knocking out DEPDC1 significantly inhibits proliferation, migration as well as invasion in colon cancer cells, as well as hinder the epithelial‐mesenchymal transition of intestinal cancer cells." (PMID 33140894, 2020). "In a recent report concerning CRC, researchers found that the expression level of DEPDC1 in CRC tissues is significantly higher than that in adjacent tissues and plays an oncogenic role in colon cancer cells." (PMID 33140894, 2020).
Epstein-Barr virus infection (1 paper, 2024). An infection that is caused by Epstein-Barr virus. "Finally, DEPDC1 and its associated immune-related genes were shown to be enriched in ‘receptor ligand activity’, ‘external side of plasma membrane’, ‘regulation of innate immune response’, and ‘Epstein-Barr virus infection’ pathways." (PMID 38564630, 2024).
esophageal cancer (1 paper, 2020). A primary or metastatic malignant neoplasm involving the esophagus. "S-588410 is a CPV comprising five human leukocyte antigen (HLA)-A*24:02-restricted peptides derived from five cancer testis antigens, DEPDC1, MPHOSPH1, URLC10, CDCA1 and KOC1, which are overexpressed in esophageal cancer." (PMID 32500232, 2020). "S-588410 is a novel CPV comprising five human leukocyte antigens (HLA)-A*24:02-restricted 9–10-mer peptides derived from five cancer testis antigens (DEPDC1, MPHOSPH1, URLC10, CDCA1 and KOC1), all of which have been found to be upregulated in esophageal cancer." (PMID 32500232, 2020).
gastric adenocarcinoma (1 paper, 2024). "For example, the DEP domain containing 1 (DEPDC1) is overexpressed in gastric adenocarcinoma tissues." (PMID 39196978, 2024). "The overexpression of DEPDC1 is correlated with metastasis and the differentiation of gastric adenocarcinoma." (PMID 39196978, 2024).
intestinal cancer (1 paper, 2020). "After further exploration, they found that down‐regulating DEPDC1 can reduce zest in intestinal cancer cells." (PMID 33140894, 2020).
liposarcoma (1 paper, 2025). A usually painless malignant tumor that arises from adipose tissue. "Further in-depth molecular biology experiments on the mechanisms underlying the increase in DEPDC1 levels in liposarcoma patients should be conducted with animal models." (PMID 40600015, 2025). "In this study, we found DEPDC1 expression was linked to the occurrence and development of liposarcoma and was negatively associated with the survival of sarcoma patients." (PMID 40600015, 2025). "We conducted the first investigation of the underlying molecular mechanisms of DEPDC1 dysregulation on the malignant phenotype of liposarcoma cells, which provided new insight into exploring the pathogenesis ofliposarcoma." (PMID 40600015, 2025). "Furthermore, the impact of DEPDC1 on cellular functions of liposarcoma cell lines and its underlying mechanisms were studied using the in vitro assays." (PMID 40600015, 2025). "The CCK-8 assay revealed that DEPDC1 overexpression enhanced proliferation, while DEPDC1 depletion reduced the proliferation rate in liposarcoma cells." (PMID 40600015, 2025). "We proposed that in liposarcoma, the expression of DEPDC1 was positively correlated with the activation of the PI3K/AKT/mTOR pathway." (PMID 40600015, 2025). "The effect of si-KIF20A antagonized the activating influence of DEPDC1 overexpression on AKT/PI3K/mTOR in liposarcoma cells." (PMID 40600015, 2025). "To further identify the expression of DEPDC1 in clinical samples, we collected liposarcoma and adjacent adipose tissue with varying degrees of malignancy and analyzed the expression of DEPDC1 across these different tissues using qPCR and IHC." (PMID 40600015, 2025). "In brief, these results indicated that DEPDC1 facilitated malignant phenotypes by modulating KIF20A in liposarcoma cells." (PMID 40600015, 2025). "We next evaluated the biological functions of DEPDC1 in liposarcoma by employing overexpression and deletion techniques in the SW872 and 93T449 cell lines." (PMID 40600015, 2025). "The deletion of KIF20A partially mitigated the promoting effect of DEPDC1 on the malignant phenotype of liposarcoma cells and the activation of PI3K/AKT/mTOR signaling pathway." (PMID 40600015, 2025). "The qPCR results revealed that the DEPDC1 mRNA level in liposarcoma tissues was significantly higher than in normal adipose tissues from the same patients with liposarcoma (n = 26), as determined by a paired t-test." (PMID 40600015, 2025). "In this study, we would explore the clinical significance and functional implications of DEPDC1 in liposarcoma." (PMID 40600015, 2025). "However, currently, the involvement of DEPDC1 in the onset and progression of liposarcoma remains unexplored." (PMID 40600015, 2025). "However, we did not perform the pharmacological inhibition of PI3K or Akt experiments to validate that DEPDC1 induces the proliferation and motility of liposarcoma cells through the PI3K/Akt/mTOR signaling pathway." (PMID 40600015, 2025). "Furthermore, we screened and analyzed liposarcoma-related data from the GEO database, and found that DEPDC1 expression was significantly elevated in dedifferentiated liposarcoma (DL) compared to well-dedifferentiated liposarcoma (WDL)." (PMID 40600015, 2025). "Furthermore, this study uncovered a novel regulatory mechanism of DEPDC1 in liposarcoma, wherein it enhanced PI3K/AKT/mTOR signaling to exacerbate malignant phenotypes." (PMID 40600015, 2025). "In vitro cell functional assays indicated that DEPDC1 acts as an oncogene in liposarcoma." (PMID 40600015, 2025). "The upregulation of DEPDC1 promoted the proliferation, invasion, and migration of liposarcoma cells, which could be reversed by downregulating KIF20A." (PMID 40600015, 2025). "Therefore, the clinical samples confirmed that the expression of DEPDC1 was positively correlated with the malignancy of liposarcoma and might hold prognostic significance for liposarcoma patients." (PMID 40600015, 2025).